CCL5 (C-C motif chemokine ligand 5)
Diseases named in the same sentence as CCL5 in open-access papers (continued):
Sharing a sentence is not in itself a finding about the gene and the disease.
cancer (continued). "Nevertheless, in cancer, CCL5/RANTES expression does occur, among others, in TAM, and for this reason, the mechanism of the effect of hypoxia on the expression of CCL5/RANTES in these cells requires further research." (PMID 32781743, 2020). "Addition of recombinant CCL5 to the healthy and cancer juxtacrine cocultures did not reveal an altered ECM morphology; matrices from group (i) remain linear and stain positively for collagen VI." (PMID 32252260, 2020). "Given altered properties of NK cells toward more stimulated states in the absence of Ccl5-PE, we examined activation status of NK cells after stimulation by cancer cells in vitro." (PMID 32218434, 2020). "CCL5/CCR5 regulates the coupling of cancer cells and mesenchymal stromal cells, and IL-17B/17-BR stimulates chemokines or enhancing inflammation, both of them facilitate the progression and metastasis of cancer cells." (PMID 33143662, 2020). "Similar to our findings, CCL5 was not upregulated with cancer cells in a paracrine relationship to non-cancer cells." (PMID 32252260, 2020). "Inhibitors of the axes of CXCL8, CCL2 and CCL5 and their receptors are also available, suggesting that treatments of TNBC cancers with combination therapies of chemokines and pro-inflammatory cytokines may provide novel treatment options for TNBC patients." (PMID 31031757, 2019). "CCL5 and CLU have previously been reported as upregulated and/or secreted in several cancer types." (PMID 31215484, 2019). "The chemokine of RANTES (CCL5) is chemotactic for T cells, eosinophils, and basophils, and plays an active role in recruiting leukocytes into inflammatory sites, as well as promoting cancer progression." (PMID 29973247, 2018). "As we found levels of the cytokines CCL5, CXCL9, CXCL10, and IL16 to indicate high CTL score across multiple cancers, we hypothesized that ATM in its role as a signal transducer may be promoting the transcription of these cytokines." (PMID 29615613, 2018). "Subsequently, p-STAT3 can induce the downstream target genes, such as CCL2, CCL5, ICAM-1, SNAI1, chitinase-3-like 1 (CHI3L1), FBJ murine osteosarcoma viral oncogene homolog (FOS), and Skp2, that promote various cellular processes for cancer progression." (PMID 28157698, 2017). "CCL5 may play a crucial effect on CCA cells invasion and metastasis, but there may be other factors also influenced on cancer cell invasion and metastasis." (PMID 29088737, 2017). "We hypothesized that CCL5 could activate Akt signaling pathway partly through CCR5, and then promoting cancer cell invasion." (PMID 29088737, 2017). "Although CCL5 can bind to some chemokine receptors such as CCR1, CCR3 and CCR5, it is unclear which particular receptor is responsible for the pharmacologic CCL5 neutralization that can suppress cancer progression in mouse xenograft models." (PMID 27136535, 2016). "They demonstrated that CD133+, but not CD133− cancer cells, expressed CCL5, with CCL5 signaling blockade abrogating and recombinant CCL5 mimicking these effects." (PMID 26328269, 2015). "Under this experimental condition CCL5 stimulates cell migration rather than cell proliferation and neutralization of CCL5 inhibits the hypoxia-induced migration of cancer cells." (PMID 24523569, 2014). "The CCL5 signaling in cancer cells has been proposed to be mediated mainly, but not necessary exclusively, via CCR5 receptor." (PMID 24204919, 2013). "Although CCL5 expression was induced in BMMSCs after interaction with OTSCC cells, signaling through CCL5/CCR5 axis does not seem to be critical for the BMMSC enhanced cancer invasion." (PMID 24204919, 2013). "The expression of CCL5 was mostly detected in inflammatory cells and in some cancer cells, but only sparse CAFs were CCL5 positive, as assessed by immunohistochemical co-localization of CCL5 and CAF marker αSMA (data not shown)." (PMID 24204919, 2013).
cancer (continued). "It’s speculated that once CCL5 binds to CCR5, it serves as an autocrine factor and activates cellular responses involved in cancer progression." (PMID 23168091, 2012). "CCL5 (previously called RANTES) was originally recognized as a product of activated T cells, and plays a crucial role in the migration and metastasis of human cancer cells." (PMID 22506069, 2012). "We have examined the effect of CCL5- or CCR5-blockers administered as single agents or in combination with a murine PDGFRβ-directed treatment, this strategy being currently under clinical evaluation for the treatment of CRC cancers." (PMID 22205974, 2011). "Moreover, corresponding to the significant interaction of chemokine module 1 with receptor module 4 (expressed on, e.g., T cells) in the analyzed PDAC patient data, we observed release of module 1 chemokines (CCL5 and CXCL10) by irradiated cancer cells with subsequent recruitment of T cell subsets." (PMID 40811032, 2025). "Additionally, we found that ANXA9 could transfer the S100A4 out of cancer cells and down regulation of ANXA9 could decreased the cytokines of IL-6, IL-8, CCL2, and CCL5." (PMID 38609357, 2024). "Besides the direct effects on CCL5/CXCL2 3’UTRs it is possible that additional indirect regulatory networks orchestrated by miR-204-5p and miR-199b-5p are at play as already demonstrated in other cancer types." (PMID 36418472, 2023). "For example, although CCL5 can enhance the anti-tumoural immune response by the recruitment of CCR5+ cells such as T, NK and DC cells, it has also been shown to recruit monocytes, macrophages, and regulatory T cells and promote cancer invasion and cancer stem cells." (PMID 35205725, 2022). "In a conclusion, our results indicated that effective dose of palbociclib could arrest the cell cycle and induce apoptosis of cancer cells; however, palbociclib might induce cell senescence and enhance migration and invasion of cancer cells via SASP-related autocrine CCL5." (PMID 37181790, 2022). "However, we found that CCL5-activated CCR1 preferentially recruited Gαi, which rarely affects the ERK kinase pathway, and that it inhibited STAT3 phosphorylation by upregulating ITPR3, which is essential for both immune activation and cancer pathogenesis." (PMID 36317881, 2022). "The significant KEGG pathways are chemokine signaling pathway (CCL5, CCL18, CCL19, CCL21, CXCL12, CXCL14, CXCL13), ​​NF-kappa B signaling pathway (CCL19, CCL21, CXCL12), intestinal immune network for IgA production (TNFRSF17, CXCL12), pathways in cancer (IGF1, CXCL12)." (PMID 35486660, 2022). "During the study of the CCL5/CCR5 axis in cancer, the main focus was on targeting the interaction through the inhibition of CCR5 with antagonists, with the inhibition of CCL5 expression with neutralizing antibodies or gene silencing and generation of CCL5-knockout mice." (PMID 36430633, 2022). "Remarkably, an additional role of NK cells in the immune response to cancer has been demonstrated by recent publications that showed NK cells controlling the levels of intratumoral cross-presenting cDC1s, by expression of FLT3 Ligand and chemokines, such as CCL5 (RANTES) and XCL-1/XCL-2." (PMID 36291830, 2022). "The highly expressed cytokine CCL5 in CD8 + T Cells, NK Cells, NKT Cells, CD4 + T Memory Cells, Plasma Cells, and Langerhans Cells work together with SDC1 and SDC4 in Cancer Cells to affect the occurrence, development, and mediation of cancer survival of cancer cells." (PMID 36401283, 2022). "In the process of module analysis and characteristic molecular screening, we selected two characteristic modules and 10 characteristic molecules (PTPRC, CD2, CD69, IRF8, CCR7, CCL5, il2rb, CXCL10, CCR5, TBX21), which could be used as biomarkers of cancer stem-like cells for GIST patients." (PMID 34925310, 2021).
cancer (continued). "Similarly, another study found that tumor cell debris, after cancer therapy, promotes survival and growth of living cancer cells in multiple tumors through the secretion of pro-inflammatory cytokines such as TNF-α, IL-6, IL-8, CCL4, and CCL5 by macrophages." (PMID 32326073, 2020). "CCL5 is produced by cancer cells and by non-malignant stromal cells at primary or metastatic sites." (PMID 32260550, 2020). "Similarly, because of a significant pro-cancer effect, it is postulated that treatment may target the functioning of CCL3/MIP-1α, CCL5/RANTES." (PMID 32781743, 2020). "Our results do not formally exclude another important possibility that CCL5 might directly affect the survival of cancer cells." (PMID 32218434, 2020). "Indeed, CAFs but not the cancer cells, are the major contributors of CCL5 in RhoA knockdown tumors as assessed by immunofluorescent staining and qRT-PCR." (PMID 31705019, 2019). "Celastrol, a substance derived from Trypterygium wilfordii, used in traditional Chinese medicine and known for anti-cancer and anti-inflammatory effects, was used for IL-6 and IL-8 inhibition, while Maraviroc, a competitive CCR5 antagonist and anti-HIV drug, served as a RANTES/CCL5 inhibitor." (PMID 30524392, 2018). "TAMs, recruited by chemokines CCL2, CCL5, and CXCL, are derived from circulating monocyte precursors and are the most important regulators of tumorigenesis, which may serve as one of the hallmarks of cancer." (PMID 28243242, 2017). "The function of CCL5 on cancer cell is not well established." (PMID 29088737, 2017). "Moreover, AG1024 treatment did not modify CCL5 expression in MDA-MB231 cells thus indicating that IGF-1 did not control CCL5 in cancer cells." (PMID 27027351, 2016). "Next, we addressed whether adipocytes may control CCL5 and IGF-1 production by cancer cells." (PMID 27027351, 2016). "In co-culture roughly all cancer cells expressed CCR5, however, in monocultures approximately only 25 % of cancer cells were positive for CCR5 suggesting that a contact with stromal cells or CCL5 induction is needed for higher CCR5 expression (flow cytometry analysis, data not shown)." (PMID 24204919, 2013). "Thus, our study supports a procancer role of host CCL5 and reveals that CCL5 levels in nonimmune tissues, such as cancer microenvironments, could be important to modulate functional states of immune cells at local tissues." (PMID 32218434, 2020). "Therefore, anti-CC2 / CCL5 and IDO inhibitor could represent new strategies for cancer treatment." (PMID 30808421, 2019). "Also tested were the virus titer (in plaque-forming units [PFU]), electron microscopy of the virus preparation with or without sonication, viral replication and cytotoxicity in cancer cells, and production and secretion of human CCL5 from the infected cells into the medium." (PMID 29085848, 2017). "The accumulated evidence indicates that the chemokine (C-C motif) ligand 5 (CCL5) and C-C chemokine receptor (CCR5), which are potent chemotactic factors for inflammatory cells, may be significantly involved in the proliferation and metastasis of several cancers." (PMID 22567084, 2012). "Similarly, vital immune checkpoint genes such as HAVR2, CD274, CTLA4, ITGB2, ICAM1, CCL5, CXCL10 all exhibited robust correlation with IFI30, and this immunotherapy might, in the future, establish a bond with IFI30, bringing new opportunities for cancer treatment." (PMID 39925804, 2025). "The role of both CCL5 and CCR5 has been elucidated in many types of cancers, expressed by cancer cells as well as non-cancerous cells in the TME." (PMID 32545571, 2020). "Another strategy to slow cancer progression at the CCL5/CCR5 axis level is inhibition of CCL5 secretion, which can also be achieved by drugs that do not have CCL5 as their target." (PMID 32630699, 2020).
cancer (continued). "A number of chemokines were significantly upregulated in cancer cell-educated BMSCs compared with non-educated BMSCs, including CXCL5 and CCL5." (PMID 31819035, 2019). "No major alterations were found between the levels of the pro-inflammatory TNF, IL6, CCL2 and CCL5 and of the anti-inflammatory CD163 in macrophages cultured in the presence of cancer cells, with or without radiation exposure." (PMID 27513864, 2016). "The results revealed that none of the CCL5, CCR1, CCR3 and CCR5 was expressed in the ovarian paracancerous tissues, whereas all these molecules were expressed in both primary cancer tissues and metastatic tissues." (PMID 25788271, 2015). "Two cytokines previously shown to mediate interactions between mesenchymal cells and cancer cells, SDF-1 and CCL5/RANTES, were represented on the array and did not produce detectable signals." (PMID 20637104, 2010). "Several genes were also, however, inconsistent with the mouse model data including CCL5, CCL20, CCL22, CCL28, CXCL10, and PDL2, suggesting that these features may not be as robustly tissue-specific across different primary cancers." (PMID 33985562, 2021). "Finally, by using a cytokine array, we verified that the release of other chemokines and interleukins, such as IL6, IL8, CCL2, CCL5, known to be involved in crosstalk between CAF and cancer cells, was not statistically different between CAF-S1 and CAF-S4." (PMID 31964880, 2020). "We speculate that the molecular cross-talk between BMMSCs and carcinoma cells leads to invasion promoting TME changes in OTSCC of which PINP, but not CCL5, could be used as prognostic marker for the OTSCC prognosis." (PMID 24204919, 2013). "When the cells were treated with a combination of cetuximab and MEK or JNK, the expression levels of CCL5, CXCL9 and CXCL10 increased, confirming that not one but multiple pathways downstream of the EGFR act in concert to block IFNγ/TNFα -induced chemokine expression by these cancer cell lines." (PMID 30192802, 2018).
inflammation (31 papers, 2008 to 2026). Aberrant reaction of the microcirculation characterized by movement of fluid and leukocytes from the blood into extravascular tissues. "There is an increase in ocular pathology due to the inflammation caused by significant production of RANTES and an increase in the expression of inflammatory genes TNFA, IL1B, CXCL10, CCL5 leading to ocular inflammation." (PMID 30274199, 2018). "Therefore, co-stimulation with TWEAK and TGF-β1 can induce the steroid-insensitive production of TSLP and CCL5 in the bronchial epithelium and may contribute to airway inflammation." (PMID 39519176, 2024).
cardiovascular disease (24 papers, 2011 to 2025). "Decreased plasma levels of CCL5 have been associated with worse morbidity and mortality from cardiovascular disease, but elevated CCL5 has been associated with increased short term mortality in patients with acute coronary disease." (PMID 34869411, 2021). "Different genetic polymorphisms for CCL5/RANTES were identified as either harmful or protective for the development of cardiovascular disease." (PMID 23029252, 2012). "There were numerous studies investigating whether serum CCL5 levels were associated with cardiovascular disease, although it should be noted that levels of circulating chemokine do not correspond to levels in tissue." (PMID 26688689, 2015). "Neutralization of IL-6 and CCL5 has been suggested to be beneficial in cardiovascular disease, including atherosclerosis." (PMID 37476204, 2023). "IL-1α, IL-12p70, and CCL5 are pro-inflammatory cytokines/chemokines that may contribute to the inflammatory pathways and the accompanying brain dysfunctions as well as peripheral inflammation-linked disorders, including cardiovascular diseases, which frequently occur in persons who use MA." (PMID 37996407, 2023). "These two experiments exhibited seemingly contrary results: CCL5 exerted a protective effect on haematopoietic regeneration, but in RT-induced cardiovascular disease, CCL5 promoted injury." (PMID 35365161, 2022). "Of all chemokines, the CC-chemokine receptors CCR1 and CCR5 and their ligand CCL5 appear to play a particular role in cardiovascular diseases." (PMID 30006564, 2018). "We created a library consisting of 24 members, screened it with the chemokine CCL5, as it is important in the pathogenesis of cardiovascular disease, and successfully recovered novel evasins." (PMID 28655871, 2017). "The data suggest that CCL5 level may be a potentially useful biomarker, and that CCL5 supplement may be a promising treatment strategy for the ageing‐related cardiovascular disorders." (PMID 38899522, 2024). "However, CXCL4 is special in cardiovascular disease, as it needs to form a heterodimer with CCL5 to promote monocyte adhesion and play an antiangiogenic role." (PMID 35668739, 2021). "C-C motif chemokine ligand 5 (CCL5) is a ligand for chemokine receptor 5 (CCR5) and has traditionally been recognized for its pro-inflammatory role in metabolic and cardiovascular diseases." (PMID 40563378, 2025). "The chemokine RANTES (regulated on activation, normal T-cell expressed and secreted)/CCL5 is involved in the pathogenesis of cardiovascular disease in mice, whereas less is known in humans." (PMID 22162987, 2011). "Interestingly, CCL5, CXCL10, and CXCL11 — which have been reported to play a key role in the pathogenesis of cardiovascular disease — appeared to be most upregulated (more than 10-fold)." (PMID 26837541, 2016).
bacterial infections (23 papers, 2008 to 2024). "Several genes identified through our experimental approach have been linked to roles in host responses to bacterial infection (CCL5, ITLN1), immune modulation (ZFP36, NFKBIA) and damage (EDN1) during PD or during episodes of PD peritonitis." (PMID 28542390, 2017). "As members of the CC chemokine subfamily, CCL-4 and CCL-5 play important roles in the inflammatory response during a variety of bacterial infections." (PMID 31783919, 2019). "Classical type 1 cytokines and chemokines (e.g., IL-2, IL-12, IFN-γ, TNF-α, MCP-1/CCL2, MIP-1α/CCL3, and RANTES/CCL5) were predominantly induced around the peak of bacterial infection, and then decreased as bacterial replication was controlled at 28 dpi." (PMID 27479584, 2016). "Upon bacterial infection, cells surrounding the infected tissue secrete chemokines including CCL5." (PMID 30835201, 2019). "In addition, some papers have reported that the CCL5 could be induced in macrophages by bacterial infections, such as Salmonella typhimurium infection, Streptococcus pyogenes infection and Lactobacillus rhamnosus infection." (PMID 22330747, 2012). "The cytolytic granules have been shown to contain chemokines such as CCL3, CCL4 and CCL5 in addition to the classical mediators of cytotoxicity (GZMB, PRF1 and GNLY), in both viral and bacterial infections, indicating their role in cytolysis." (PMID 38501302, 2024). "Most of these chemokines and cytokines, such as CCL5, CCL22, IL-1β, and TNF-α, are critical to “pre-condition” the lungs to become invulnerable to bacterial infections or promote bacterial clearance during lung infections." (PMID 35677203, 2022). "In the case of activation of platelets as a result of a bacterial infection, these cells, among others, affect the CXCL4 (PF-4) and CCL5 (RANTES) chemokine receptors on the surface of the vascular endothelium, induce "extravasation" of leukocytes." (PMID 34970260, 2021). "The leading edge genes driving the enrichment of the inflammatory response pathway in response to bacterial infections included several relevant for T‐cell activation (IL1B, CCL5, TNFSF10, GPR183, CD69, SELL), suggesting that cDC2s were undergoing conventional maturation." (PMID 34333764, 2022).